CXCL10 (C-X-C motif chemokine ligand 10)
Diseases named in the same sentence as CXCL10 in open-access papers (continued):
Sharing a sentence is not in itself a finding about the gene and the disease.
tuberculosis (124 papers, 2005 to 2026). A chronic, recurrent infection caused by the bacterium Mycobacterium tuberculosis. "CXCL10 is also a reliable diagnostic and treatment-response biomarker for tuberculosis in children and adults." (PMID 41452432, 2025). "For example, a single polynucleotide polymorphism (SNP) in the Cxcl10 promoter (−135G>A) enhanced its transcriptional activity in tuberculosis." (PMID 25405070, 2014). "Polymorphisms in the CXCL10 gene have been associated with diabetes, hepatitis, tuberculosis, Alzheimer's disease, and multiple sclerosis." (PMID 24349056, 2013). "Single nucleotide polymorphisms (SNPs) in the CXCL10 gene have been described to be associated with diabetes, hepatitis, tuberculosis, Alzheimer's disease, and multiple sclerosis." (PMID 24349056, 2013). "In line with its cardinal role in immune control of M. tuberculosis infection, CXCL10 has emerged as a potential correlate for treatment efficacy as well as a measure of TB disease severity and correlate of risk." (PMID 30026741, 2018). "CXCL10 is elevated in several diseases, including hepatitis B, tuberculosis, cancer, diabetes, and autoimmune disorders." (PMID 37493737, 2023). "Both immunohistochemical staining and qRT-PCR indicated that the expressions of IL-27, CXCL9, CXCL10, and CXCL11 were significantly increased in tuberculosis patients, and IL-27 was significantly correlated with CXCL10 (r = 0.68)." (PMID 35785034, 2022). "In previous studies, the high expression of IL-27, CXCL9, and CXCL10 in the peripheral serum, pleural effusion, and bronchial lavage fluid of tuberculosis patients used in the diagnosis and differential tuberculosis has a good performance." (PMID 35785034, 2022). "In this study, in order to further explore the role of IL-27 and CXCL10 in tuberculosis, we continue to use bioinformatics methods to combine the prediction results of miRWalk, TarBase, miRDB, miRSystem, and TargetScanHuman." (PMID 35785034, 2022). "As well as in several autoimmune diseases and in infections with various viruses, CXCL10 has been reported to be a useful biomarker for tuberculosis (TB)." (PMID 30885152, 2019). "In association with this, the expression pattern of many STAT-1 mediated proinflammatory pathway genes, including Cxcl10 (IP-10) and Ccl20 that are considered biomarkers of active Tb disease, were also downregulated in the ΔbfrB vaccinated mice lungs." (PMID 26339659, 2015). "Chemokines such as CXCL10 have been used as additional read-outs for blood-based IFN-γ release assays of human tuberculosis." (PMID 22359547, 2012). "Our in situ hybridization data confirm that in contrast with normal lung tissue preparations a strong expression of CXCL10 can be detected in sarcoidosis and tuberculosis – diseases in which the Th1-type cytokine IFN-γ is up-regulated." (PMID 16033640, 2005). "Moreover, a number of biomarkers, such as IFN-γ, CXCR3, CXCL9, CXCL10, and a combination of miRNAs, have demonstrated notable significance in the diagnosis of subclinical tuberculosis (STB)." (PMID 39274240, 2024). "In the meantime, CXCL10 overexpression has been repeatedly observed in tuberculosis patients." (PMID 36845395, 2023). "CXCL10 is a major biomarker for active tuberculosis and is induced by IFN-γ." (PMID 36051240, 2022). "Furthermore, markers elevated in Stage 1, such as CRP and CXCL10/IP-10, have been found to have high sensitivity and moderate specificity to triage patients with symptoms suggestive of active tuberculosis." (PMID 33724185, 2021). "We aimed to explore whether such CXCL10 antagonism may have an impact on the pathogenesis of tuberculosis (TB)." (PMID 30026741, 2018). "Surprisingly CXCL10 has been implicated in several diseases including CM, Toxoplasma gondii, tuberculosis, candidiasis, West Nile Virus, hepatitis B virus, and HIV suggesting that CXCL10 may confer susceptibility to these infections." (PMID 24349056, 2013).
tuberculosis (continued). "Finally, active tuberculosis and pregnancy, two exclusion criteria in this study, have also been reported as modulating the level of CXCL10." (PMID 19554086, 2009). "CXCL10 is upregulated in the human lung during active TB, recruiting CD4+ T cells to the lungs via CXCR3 during M. tuberculosis infection." (PMID 37896952, 2023). "In our next research, we will further explore the important roles of let-7b-5p and miR-30a-3p in tuberculosis and their relationship with IL-27 and CXCL10, hoping to have a better understanding on resistance M. TB process." (PMID 35785034, 2022). "Diagnostic performance of the CXCL10 mRNA release assay and T-SPOT.TB assay for Mycobacterium tuberculosis (M.tb) infection." (PMID 35432271, 2022). "CXCL10 has been used to distinguish between tuberculosis and latent tuberculosis, and a significant decrease in CCL4 expression was observed in individuals with latent tuberculosis after antituberculosis treatment associated with a decreased risk of developing active tuberculosis." (PMID 34722780, 2021). "Thus, a baseline chemokine signature of CCL1/CXCL1/CXCL10 could serve as an accurate biomarker for the diagnosis of pediatric tuberculosis." (PMID 34635070, 2021). "The data suggest that in TB, CXCL10 is secreted by M. tuberculosis-infected macrophages, and undergoes rapid inactivation by membrane bound DPP4 (CD26) expressed on co-localized CD4+ T cells." (PMID 30026741, 2018). "Interestingly, the CXCL10/CXCR3 interaction played an important role in tuberculosis." (PMID 24732949, 2014). "Spouses with positive IFN-γ responses to M. tuberculosis ESAT-6 (>62.5 pg/mL) and TB patients showed high production of IL-17, CXCL10 and TNF-α." (PMID 24260295, 2013). "CXCL10, induced by interferon-gamma (IFN-gamma), is integral to the immune response against tuberculosis, as it aids in the recruitment of immune cells to the infection site and contributes to granuloma formation—a hallmark of TB pathology." (PMID 40164948, 2025). "The increase in CXCL10, despite stable IFN-γ levels, indicates an age-related enhancement of downstream IFN-γ signaling, highlighting CXCL10’s potential as a tuberculosis marker in children." (PMID 41452432, 2025). "CXCR3 antagonism via truncated CXCL10 may also be an important regulatory mechanism occurring in tumors and in sites of tuberculosis (TB) pathology." (PMID 37896834, 2023). "In this study, we used immunohistochemistry to detect the expression levels of IL-27, CXCL9, CXCL10, and CXCL11 in patients with tuberculosis and observe their expression in the lesion." (PMID 35785034, 2022). "More recently, some studies have reported the association between sputum conversion at 60 day of TB treatment with decreases in serum levels of CRP, CXCL10, IL-17, MMP-8, as well as with cytokine responses after M. tuberculosis-specific in vitro stimulation of peripheral blood." (PMID 27494953, 2016). "This is especially interesting because neutrophils from patients with active tuberculosis also exhibit an IFN-induced transcriptome profile, including increased expression of CXCL10 and CD274." (PMID 24015224, 2013). "Among the chemokines, CXCL10/IP10, a chemokine induced by IFN- γ has shown promising results as marker of tuberculosis disease in children." (PMID 21991356, 2011). "CXCL10 has been proposed to be an immune marker of disease progression in HIV and tuberculosis patients and was increased in sarcoidosis patients' serum." (PMID 19473542, 2009). "CXCL10 is however not specific for viral pneumonia, as it is upregulated by type I/II interferons, which can be activated by bacterial (e.g. tuberculosis), viral and non-infectious (e.g. autoimmune disease) processes." (PMID 41307734, 2025). "Previously, we described elevated levels of cytokines/chemokines such as IL-18, IFN-γ, CXCL-10, CXCL-9, G-CSF, IL-6, CXCL-1, VEGF, and PDGF-BB in plasma samples of tuberculosis (TB) patients with active pulmonary disease." (PMID 37685858, 2023).
tuberculosis (continued). "Performance of the CXCL10 mRNA release assay and T-SPOT.TB assay among tuberculosis (TB patients) with HIV co-infection." (PMID 35432271, 2022). "CXCL10, also known as interferon γ-induced protein 10 (IP-10), similar to CXCL9, can be secreted by various cells, including monocytes, leukocytes, endothelia, and epithelia, and is up-regulated in numerous diseases, including hepatitis B, tuberculosis, cancer, diabetes, and autoimmune disorders." (PMID 31836011, 2019). "Our data bridges previous observations of high levels of CXCL10 and CD26 in TB pleural effusions and of CXCL10 expression in lungs of non-human primates experimentally infected with M. tuberculosis." (PMID 30026741, 2018). "IP-10/CXCL10 and IL-8/CXCL8 are involved in neutrophil and lymphocyte recruitment against M. tuberculosis (MTb) and disease progression of pulmonary tuberculosis (TB)." (PMID 24223729, 2013). "A recent prospective case-control study of children with and without tuberculosis found that baseline levels of CXCL1 and CXCL10 were exclusively higher in the infected people and decreased after anti-TB treatment." (PMID 36164329, 2022). "In subjects with active tuberculosis, IFN-α2 and IFN-γ proteins were not elevated in serum although as for CVID subjects, IFN-inducible chemokine CXCL10 (IP10) and other IFN responsive genes, were significantly increased." (PMID 24069364, 2013). "For example, the plasma levels of IL-18, CCL-2, and CXCL10 differed depending on whether patients developed TB IRIS without a previous episode (unmasking IRIS) or developed it as an unexpected worsening of tuberculosis (paradoxical IRIS)." (PMID 23688318, 2013). "CXCL10 and TNF-α may be used as adjunct markers alongside an IFN-γ release assay to diagnose M. tuberculosis infection, and IL-17 and IL-10 production may differentiate individuals with LTBI from active TB." (PMID 24260295, 2013).
autoimmune disease (116 papers, 2006 to 2026). A disorder resulting from loss of function or tissue destruction of an organ or multiple organs, arising from humoral or cellular immune responses of the individual to their own tissue constituents. "TNF and CXCL10 are critical cytokines involved in inflammatory responses and immune cell activation, associated with various autoimmune diseases." (PMID 41383128, 2025). "Our findings demonstrate a causative link between specific autoimmune diseases and rhinosinusitis, highlighting IL-10, CXCL10, and CD6 as potential mediators in this association." (PMID 39104791, 2024). "C-X-C chemokine ligand 10 (CXCL10), also known as interferon γ-induced protein 10 (IP-10), is a chemokine with a pathogenic role in autoimmune diseases that features among the main myokines involved in the pathogenesis and progression of myositis." (PMID 37891738, 2023). "The results of GSEA showed that antigen processing and presentation, autoimmune disease-associated pathways, and cytosolic DNA-sensing pathway were obviously enriched in Cxcl10+Sirpa+ cDC2 subcluster." (PMID 36209176, 2022). "CXCL10 chemokine is an IFNγ-inducible 10-kDa protein implicated in the pathology of many autoimmune diseases through the recruitment and activation of T cells, neutrophils and monocytes." (PMID 30250011, 2018). "Both excessive and deficient CXCL10 production by PBMC upon IFN stimulation has been described for other autoimmune disorders with a defined peripheral IFN signature, such as SLE and rheumatoid arthritis (Karonitsch and others 2009, 2012)." (PMID 25978633, 2015). "Among chemokines, CXCL10 plays a critical role in the initiation and maintenance of Th1-polarized response in autoimmune diseases or in graft injury; it appears to be directly linked to the disease pathogenesis and not related to a generic inflammatory status." (PMID 23690671, 2013). "While most CXCL10 antibodies are still in preclinical or early clinical development, they are also being investigated for inflammatory and autoimmune diseases such as rheumatoid arthritis, multiple sclerosis and inflammatory bowel disease, where aberrant CXCL10 expression plays a pathogenic role." (PMID 40760734, 2025). "C-X-C motif chemokine ligand 10 (CXCL10), also referred to as interferon gamma (IFN-γ)-inducible protein (IP-10), has been associated with the immune-pathogenesis of several autoimmune diseases such as GD via its receptor CXCR3 (chemokine (C-X-C motif) receptor 3)." (PMID 39329107, 2024). "However, it should be underlined that DQT inhibits both IFNβ and CXCL10, which play critical pathogenic roles in many autoimmune diseases." (PMID 30250011, 2018). "Therefore, DQT may be regarded as a new promising inhibitor of IFNβ expression and IFNβ-dependent downstream genes and proteins, e.g., CXCL10 chemokine, which is implicated in the pathogenesis of autoimmune diseases." (PMID 30250011, 2018). "In autoimmune diseases such as rheumatoid arthritis, systemic lupus erythematosus and multiple sclerosis, elevated CXCL10 levels are a sign of an active immune response and disease exacerbation." (PMID 40760734, 2025). "The interferon-γ-stimulated secretion of cytokines like CXCL10 is a key mechanism in autoimmune diseases (including SLE) perpetuating inflammation and autoimmunity, potentially favoring carcinogenesis." (PMID 40225477, 2025). "Intriguingly, CXCL10 has also been shown to play a central role in the pathogenesis of other autoimmune diseases." (PMID 39436967, 2025). "To assess the activity of BLUE compounds in the context of autoimmune disease associated with aberrant type I IFN activation, we also measured ISG expression and CXCL10 secretion levels of PBMCs from participants affected by SSc25." (PMID 40097626, 2025). "CXCL10 levels are elevated in a wide range of autoimmune diseases and, although we found that it is elevated in responders, is a pleotropic cytokine in need of additional research on its role in response to omalizumab." (PMID 38710930, 2024).
autoimmune disease (continued). "The IFNγ-inducible chemokine CXCL10 has been implicated in T- and NKT-cell recruitment via receptor CXCR3 in autoimmune disease, various inflammatory conditions and cancer." (PMID 39007345, 2024). "According to this, the inhibition of CXCL10 is considered beneficial in treating T-cell-mediated autoimmune diseases such as rheumatoid arthritis and type I diabetes." (PMID 36912171, 2023). "CXCL10 is involved in immune response, host defense against viral and bacterial infections, and several inflammatory and autoimmune diseases." (PMID 38107572, 2023). "CXCL10 is induced by both type I and type II interferon and has been evaluated as a biomarker for disease activity in many autoimmune diseases." (PMID 38124139, 2023). "In autoimmune diseases, CXCL10 contributes to tissue damage by promoting the infiltration of immune cells into affected tissues." (PMID 38107572, 2023). "Apart from pSS, a number of other autoimmune diseases are thought to be influenced by CXCL10, which recruits immune cells to sites of inflammation." (PMID 37244954, 2023). "CXCL10 is also known as interferon (IFN)-γ-inducible protein 10 (IP-10), CXCL10 participates in various immune responses such as various autoimmune diseases of the human body, tumor immunity, organ transplant rejection, etc." (PMID 35480323, 2022). "Chemokine CXCL10 has been predicted to play an important role in leucocyte recruitment and immune response in a number of inflammatory and autoimmune diseases." (PMID 34659199, 2021). "Recently, it has been shown that CXCL10 plays a vital role in autoimmune disease development, such as inflammatory bowel disease and type 1 diabetes through enhancing the Th1 autoimmune response." (PMID 34481469, 2021). "Anti-CXCL10 monoclonal antibodies have implications in infectious disease, chronic inflammatory, and autoimmune disease therapeutics and attenuate murine inflammatory bowel disease and murine AIDS colitis." (PMID 34202278, 2021). "Despite the “signal zero”, triggering autoimmune diseases are yet to be identified in most cases, including SSc, and the role of chemokines such as CXCL10 in amplifying and directing the inflammatory events is well characterized." (PMID 33809279, 2021). "High levels of CXCL10 in humoral components, such as peripheral blood and joint fluid, are typical of various autoimmune diseases, especially those with a predominance of Th1 cells (Lee, Lee & Song, 2009)." (PMID 34040897, 2021). "Studies have also suggested associations between the disease activity of autoimmune diseases and serum or BALF CXCL9, CXCL10, and CXCL11 levels in patients with SLE, DM, or SScs." (PMID 33137121, 2020). "Previous literature has reported significantly increased CXCL10 in the active phase of rheumatoid arthritis, Sjogren's syndrome, systemic lupus erythematosus, and other autoimmune diseases." (PMID 33408682, 2020). "CXCL10 expression is increased in such autoimmune disorders as psoriasis, diabetes, rheumatoid arthritis, systemic sclerosis, systemic lupus erythematosus, Sjögren’s syndrome and idiopathic inflammatory myopathy." (PMID 30250011, 2018). "Serum CXCL10 has been shown to be increased in patients with various autoimmune diseases including rheumatoid arthritis, systemic lupus, and Sjogren’s syndrome." (PMID 29456540, 2018). "The pro-inflammatory chemokine CXCL10 has been reported to attract activated macrophages, T cells, and NK cells to the site of inflammation and is upregulated in autoimmune diseases, including RA." (PMID 30231487, 2018). "Recently CXCL10 has been shown to play a role in autoimmune disease, in particular type 1 diabetes and inflammatory bowel disease, through the augmentation of the Th1 autoimmune response." (PMID 29426834, 2018). "During systemic inflammation CXCL10 is produced by monocytes and endothelial cells in a variety of pathologies, which include autoimmune diseases, inflammatory bowel diseases, chronic liver diseases and especially hepatitis C." (PMID 28821016, 2017).